UGT3A1 (UDP glycosyltransferase family 3 member A1)
Description:
Involved in biotransformation reactions in which lipophilic substrates are conjugated with sugars to increase water solubility and enhance excretion. Such reactions are of major importance in the elimination of potentially toxic xenobiotics and endogenous compounds. It catalyzes the transfer of N-acetylglucosamine from UDP-N-acetylglucosamine to the bile acid ursodeoxycholic acid (UDCA). UDP-N-acetylglucosamine is the preferred sugar donor, while the enzyme has low activity with UDP-glucose and UDP-galactose. Is inactive with UDP-xylose and UDP-glucuronic acid as sugar donors. In addition to UDCA, it can use, to a lesser extent, 17alpha-estradiol, 17beta-estradiol, 4-nitrophenol and 1-naphtol as sugar acceptors. Has very low activity with 4-methylumbelliferone and genistein as sugar acceptors, and has negligible activity, if any, toward cholic acid, chenodeoxycholic acid, deoxycholic acid, lithocholic acid, and hyodeoxycholic acid.
Synonyms: FLJ34658
Tractability: Antibody: UniProt predicts a signal peptide or a membrane-spanning region.
Gene: Protein-coding gene on chromosome 5 (35,951,006 to 36,001,028, reverse strand). Ensembl gene ENSG00000145626.
Subcellular location: Membrane
Subcellular location (Human Protein Atlas): Cytosol; Vesicles
Pathways (Reactome):
Drug ADME: Aspirin ADME
Metabolism: Glucuronidation
Gene Ontology:
Molecular function: glucuronosyltransferase activity; UDP-glycosyltransferase activity; isoflavone 7-O-glucosyltransferase activity
Cellular component: UDP-N-acetylglucosamine transferase complex; membrane
Genetic constraint (gnomAD): Loss-of-function variants: 31 observed, 33.41 expected, observed/expected ratio (o/e) 0.93, 90% interval 0.7 to 1.25. The upper end of that interval is the gene's LOEUF score, 1.25, which puts it in group 5 of 6, group 1 being the genes least tolerant of losing a copy. Missense variants: 621 observed, 642.64 expected, observed/expected ratio (o/e) 0.97, 90% interval 0.9 to 1.03. Synonymous variants: 250 observed, 238.09 expected, observed/expected ratio (o/e) 1.05, 90% interval 0.95 to 1.17.
Homologues: Orthologues: chimpanzee UGT3A1 (97% identical), macaque UGT3A1 (93% identical), zebrafish ugt2b5 (32% identical), zebrafish ugt2b1 (31% identical), zebrafish ugt5a2 (31% identical), zebrafish ugt2a7 (30% identical), zebrafish ugt5a1 (30% identical), zebrafish si:ch73-334d15.1 (29% identical), zebrafish ugt5e1 (29% identical), zebrafish ugt5g2 (29% identical), zebrafish ugt5b4 (29% identical), zebrafish ugt5g1 (28% identical), and 95 more. Paralogues in human: UGT3A2 (78% identical), UGT2B7 (31% identical), UGT2A3 (31% identical), UGT2A2 (31% identical), UGT2B4 (31% identical), UGT2B10 (30% identical), UGT2B15 (30% identical), UGT1A1 (30% identical), UGT2B17 (30% identical), UGT8 (30% identical), UGT2B28 (29% identical), UGT2B11 (29% identical), and 9 more.
Diseases named in the same sentence as UGT3A1 in open-access papers:
UGT3A1 is named in the same sentence as 3 diseases in open-access papers, as found by Europe PMC text mining. Sharing a sentence is not in itself a finding about the gene and the disease. The quoted sentences say what the papers report.
lung adenocarcinoma (1 paper, 2018). A carcinoma that arises from the lung and is characterized by the presence of malignant glandular epithelial cells. "Moreover from The Cancer Genome Atlas (TCGA) database, hsa-miR-181a-5p was identified as an oncogene that targeted UGT3A1 in lung adenocarcinomas." (PMID 29695969, 2018).
cancer (1 paper, 2021). A tumor composed of atypical neoplastic, often pleomorphic cells that invade other tissues. "Expression of UGT3A1 was high in cancers associated with the hepatobiliary and renal excretion systems (CHOL, KIRC, KIRP, LIHC)." (PMID 34503303, 2021).
UGT3A1 also shares sentences with these, for which no sentence is quoted: Smith-Lemli-Opitz syndrome (1 paper).